RNU6-903P (RNA, U6 small nuclear 903, pseudogene)
Gene: Small nuclear RNA gene on chromosome 18 (9,617,964 to 9,618,072, reverse strand). Ensembl gene ENSG00000212572.
Homologues: Orthologues: chimpanzee U6 (96% identical), pig U6 (77% identical). Paralogues in human: RNU6-116P (81% identical), RNU6-10P (80% identical), RNU6-1147P (80% identical), RNU6-1060P (79% identical), RNU6-1123P (79% identical), RNU6-196P (79% identical), RNU6-1175P (78% identical), RNU6-1201P (78% identical), RNU6-12P (78% identical), RNU6-13P (78% identical), RNU6-24P (78% identical), RNU6-32P (78% identical), and 1282 more.